IL17A (interleukin 17A)
Diseases named in the same sentence as IL17A in open-access papers (continued):
Sharing a sentence is not in itself a finding about the gene and the disease.
asthma (continued). "In asthma patients, elevated levels of IL-17A and IL-17F are found in the airways and BALF that positively correlate with disease severity and neutrophil inflammation." (PMID 34777398, 2021). "Several studies have shown elevated IL17A mRNA expression in severe asthma, some of which have reported IL17A signalling involvement in the mobilisation of neutrophils and smooth muscle cells in the airways." (PMID 33784348, 2021). "In contrast, the pathobiology of T2-low asthma typically involves Th1 and Th17 cells, neutrophils and several proinflammatory cytokines such as IL-1β, IL-6, IL-17A, IL-17F, IFN-γ and TNF-α." (PMID 34777398, 2021). "The expression of IL-17A in the lung tissue of asthma patients and HCs showed a strong correlation with the expression of STAT3 and SOCS3." (PMID 34760922, 2021). "IL-17A levels are upregulated in the lung tissues of patients with asthma, and the level of IL-17 correlates with asthma severity in patients with neutrophilic asthma." (PMID 33806085, 2021). "Concerning asthma therapy through the inhibition of IL-17A, two humanized monoclonal antibodies with different mechanisms of action are currently considered." (PMID 35055325, 2021). "For instance, Th17 cells, the main cellular source of this cytokine, were refractory to inhibition with glucocorticoids in asthma, especially, when IL-17A and IL-22 were co-expressed in these cells." (PMID 33717165, 2021). "Vitamin D supplementation reduces the blood IL-17A levels while increasing IL-10 levels in asthma patients, according to the experimental research." (PMID 34944659, 2021). "The BM-MSCs IT injection in OVA-induced asthma decreased eosinophilia, lymphocyte, total protein, IL-13, and IL-17A levels and significantly decreased airway remodeling, which persisted for 14 days after the injection." (PMID 33959015, 2021). "Th17 cells producing IL-17A also contribute to lung inflammation in asthma with accumulated neutrophils." (PMID 34691038, 2021). "Alveolar macrophages from COPD patients and healthy subjects express both IL-17A and IL-17F7 and cells positively immunostained for IL-17A are increased in the airway submucosa in patients with severe asthma and COPD8." (PMID 34075087, 2021). "Secondly, in this study, the IL-17A mRNA significantly increased in the mixed phenotype of asthma patients compared with pauci-granulocytic phenotype." (PMID 34344357, 2021). "IL-17A is widely reported to regulate chronic inflammatory diseases, including respiratory diseases such as asthma." (PMID 34001091, 2021). "During the onset of asthma, stimulation of the Th17/IL-17A axis leads to the release of neutrophil chemoattractants and their accumulation in the airways stimulates the development of neutrophil-based asthma with increasing severity." (PMID 35387016, 2021). "Several studies have reported higher levels of IL-17, notably IL-17A and IL-17F, in sputum, nasal and bronchial biopsies, and blood of patients with severe asthma as compared to those with mild asthma." (PMID 35387016, 2021). "In the majority of asthma patients, primary bronchial epithelial cells were hyperresponsive to IL-17A and proinflammatory stimuli such as TNF-α, reflected by an enhanced production of inflammatory mediators such as CXCL-8, and corticosteroid insensitivity." (PMID 34221070, 2021). "Several preclinical and clinical studies reported relatively high level of IL-17, particularly IL-17A and IL-17F, in sputum, nasal and bronchial biopsies, and blood of patients with severe asthma." (PMID 35387016, 2021). "We also investigated the effect of VitD supplementation on the expression of proinflammatory cytokines involved in asthma pathogenesis, including Th2 cytokines (IL-4 and IL-5) and Th17 cytokines (IL-17A and IL-17F)." (PMID 34395637, 2021). "In a mixed Th2/Th17 mouse model of steroid-insensitive asthma, IL-17A was shown to be an independent contributor to AHR." (PMID 35387016, 2021).
asthma (continued). "Previously, we found that treatment with the IL-17A monoclonal antibody reduced corticosteroid insensitivity in a mouse model of asthma." (PMID 34760922, 2021). "In mild-to-moderate asthmatics, the level of IL-17A in the airway submucosal layer was significantly increased, whereas IL-17F was higher in both mild-to-moderate and severe asthma." (PMID 35387016, 2021). "IL-17A interacts with various immune factors to contribute to lung remodeling in TH17-driven endotypes of severe asthma." (PMID 34221020, 2021). "Another study investigated the role of IL‐17A and IL‐17E also measured by ELISA in children with allergic diseases (AD, hay fever, and asthma) in patients with food allergies." (PMID 34429872, 2021). "Perhaps a more interesting finding was that certain T-cell populations in asthma patients can produce both IL-17A and IL-4, and such cells appear to be a combination of Th17 (an immune response involving IL-17 and separate from Th1 and Th2) and Th2." (PMID 33526116, 2020). "The lowest IL-17A mRNA expression in asthma was observed in moDCs cultured with epithelium compared to respective co-cultivation scheme in the control group." (PMID 32842623, 2020). "BMI correlated significantly with IL-17A mRNA expression in moDCs co-cultivated with epithelium (r = −0.745, p = 0.010) in the asthma group only." (PMID 32842623, 2020). "CAM attenuates airway inflammation via TNFα and IL-17A suppression in a mouse model of steroid-resistant asthma." (PMID 31820024, 2020). "Meanwhile, IL-17A was shown to contribute to all asthma characteristics, including inflammatory cells infiltration, mucus hypersecretion, tissue remodeling, and AHR." (PMID 32938460, 2020). "Substantial evidences showed that IL-17A were significantly increased in the airways of patients with asthma, and closely correlated with main clinical parameters of asthma." (PMID 32938460, 2020). "The aim of the study was to evaluate the impact of interactions between DCs and nasal epithelial cells co-cultured with macrophages on the expression of TSLP, IL-33, and IL-17A in asthma, COPD, and controls." (PMID 32842623, 2020). "Recent studies indicate a function for IL-17A/F and the IL-17 receptors IL-17RA and IL-17RC in models of experimental asthma." (PMID 32641167, 2020). "The findings suggested that OVA exposure contributed to the remarkable elevation of IL-4, IL-5, IL-13, and IL-17A level in asthma group mice compared with control group mice." (PMID 33013383, 2020). "The increased level of IL-17A or its mRNA were detected in sputum, bronchial tissues, and serum of patients with asthma." (PMID 32410853, 2020). "One of the major proinflammatory cytokines involved in obesity as well as asthma is IL-17A.The role of Th17 cells in obesity is relatively unexplored but evidence of accumulation of Th17 cells in a mouse model of diet-induced obesity has been described." (PMID 32849611, 2020). "Women with severe asthma also showed a higher IL-23R expression and IL-17A production by Th17-differentiated cells when compared with severely asthmatic men." (PMID 32610544, 2020). "The mechanism of the asthma-suppressive effect in Tlr9−/− mice relied on the over-induction of IL-17A, creating a situation of Th17 activation that antagonized Th2 inflammation." (PMID 33093516, 2020). "The treatment of asthma by omega-3 fatty acids is more effective than sublingual immunotherapy to reduce the level of IL-17A." (PMID 32395125, 2020). "Studies have reported that ER stress contributed to neutrophil inflammation in response to 4-PBA treatment and IL-17A neutralization in the animal models of acute lung injury and severe asthma." (PMID 33371364, 2020). "In a recent study on neutrophilic inflammation in asthma, it was shown that Dexa and IL-17A in combination synergistically induced the expression of the neutrophil promoting cytokine CSF3 and Dexa alone failed to alleviate neutrophilic inflammation." (PMID 32849611, 2020).
asthma (continued). "Cultured ASMCs exposed to IL-13 and/or IL-17A showed a robust transcriptional response to these asthma-promoting cytokines." (PMID 32690065, 2020). "Th17 cells produce IL-17A and IL-17F, whose expression was shown to be significantly up-regulated in bronchial biopsies from patients with severe asthma." (PMID 33329598, 2020). "Next, we used anti-mouse IL-17A neutralizing antibodies to further verify the asthma suppressive effect of the over-producing IL-17A." (PMID 33093516, 2020). "IL-17A and IL-17F production is increased with severity of the disease and Th17 cells are now recognized as the major T helper subset in severe asthma." (PMID 32849611, 2020). "IL-17A levels in the serum were significantly higher in the asthma group, compared to the normal group (P<0.05)." (PMID 33053115, 2020). "Moderate asthma and severe asthma are usually related to the increase of neutrophils and Th17 cytokines such as IL-17A, IL-17F, and IL-22 producing the secretion of epithelial-derived neutrophil chemokines to attract neutrophils in the airways." (PMID 32015750, 2020). "TSLP, IL-33, and IL-17A expression in moDCs are differently regulated by epithelium in asthma, COPD, and healthy subjects." (PMID 32842623, 2020). "We and other groups have reported neutrophils as a source of IL-17A in asthma patients where an increased frequency of IL-17A+ neutrophils was observed, especially in patients with asthma allergy to fungus." (PMID 31388340, 2019). "In patients with severe asthma, IL-17A production was increased to a greater degree in TH17 cells from women compared with those from men." (PMID 31071965, 2019). "We demonstrated that S. commune induces neutrophilic airway inflammation in OVA-induced asthma model mice, and IL-17A and IL-17F had central roles in this activity." (PMID 31852931, 2019). "Further reports supported the role of IL-17A in a neutrophil- and macrophage-mediated inflammation, appearing also in our asthma model." (PMID 31779093, 2019). "Intratracheal administration of S. commune to the OVA-induced asthma model mice induced the production of the Th17-related cytokines, IL-17A and IL-17F, as well as Th1-related cytokine INF-γ in the lungs." (PMID 31852931, 2019). "We further found that seminal fluid from middle-aged human volunteers had beneficial effects in asthmatic female mice; these effects were associated with transcriptional repression of osteopontin and IL-17A, which are poor prognostic factors for asthma." (PMID 30677748, 2019). "Recent studies illustrated the upregulation of IL-17A and IL-17F in asthma and reported that elevation of IL-17A and IL-17F levels in the lungs is directly correlated with disease severity." (PMID 31852931, 2019). "In conclusion, we demonstrated that the basidiomycetous fungus S. commune induces neutrophilic airway inflammation in OVA-induced asthma model mice, while IL-17A and IL-17F play central roles in neutrophilic airway inflammation induced by S. commune." (PMID 31852931, 2019). "In particular, airway concentration of IL-17 and its related cytokines (IL-17A and IL-25) are upregulated in patients with uncontrolled asthma; their levels have been positively correlated to neutrophilic inflammation and asthma severity." (PMID 31355170, 2019). "In line with our findings, these data suggest that S. commune can exacerbate asthma by inducing IL-17A– and IL-17F–mediated neutrophilic airway inflammation." (PMID 31852931, 2019). "The pathogenesis of TDI-induced asthma in at least one mouse model depends on the Th17 response: IL-17A suppresses TH2 inflammation with eosinophil recruitment, whereas IL17F drives Th17 inflammation and neutrophil increase in airways." (PMID 31816917, 2019). "In studies involving the Th17 pathway, SNVs in the IL17A and the IL17F were associated with allergic rhinitis and asthma." (PMID 31168303, 2019).
asthma (continued). "To understand how miR-146a expression is regulated in the airway epithelial cells, we stimulated primary cultured HBECs from healthy donors with cytokines associated with asthma pathogenesis, including IFN-γ, TNF-α, IL-17A, IL-22 and IL-4." (PMID 31798831, 2019). "The cytokines that comprise part of the Th17 response (IL-1β and IL-17A) and are important in promoting the secretion of pro-inflammatory cytokines were significantly elevated in RV-C-infected children with asthma compared to controls." (PMID 31703379, 2019). "In the present study, the potential role of two key cytokines of IL-10 and IL-17A was investigated in asthma pathogenesis." (PMID 30915130, 2018). "The fold change analysis of IL-17A expression showed a correlation with severity of asthma so that its expression level showed a meaningful pattern for mild and severe asthma compared to the healthy control." (PMID 30915130, 2018). "In this study, we evaluated the expression alteration of Interleukin-10 (IL-10) and Interleukin-17A (IL-17A) in some categories of asthma patients with different level of severity versus healthy controls." (PMID 30915130, 2018). "IL17A and Th17 cells have been shown to play an important role in the pathophysiology of airway diseases such as asthma and COPD." (PMID 29724254, 2018). "In comparison with control population, obtained data showed 4 and 7-fold down-regulation of IL-17A in the group of mild and severe asthma, respectively." (PMID 30915130, 2018). "Further, IL17A has been shown to play an important role in the severity of human airway diseases, such as asthma and COPD." (PMID 29724254, 2018). "Noteworthy, the down-regulation of IL-17A is more distinctive in all asthma samples in comparison with IL-10 expression level." (PMID 30915130, 2018). "Obtained data revealed that deregulation IL-10 and IL-17A have potential to play crucial role in pathogenesis and prognosis of asthma." (PMID 30915130, 2018). "Association studies also show a correlation of IL-17 with early-childhood asthma, and current investigation demonstrates a relationship between IL-17A and asthmatic diseases." (PMID 31826038, 2018). "In this study, we compared the mRNA expression of IL-10 and IL-17A in three distinct groups of healthy control, mild and severe asthma to investigate any relationship between these interleukins with the severity of asthma." (PMID 30915130, 2018). "It is proposed that IL-17A can therefore induce neutrophilic airway inflammation and promote steroid resistance in adults with severe asthma." (PMID 27746241, 2017). "In conclusion, we found that elevated plasma IL-17A and IL-9 levels and decreased plasma expressions of adipsin and CCL11 were positively associated with asthma risk in adults." (PMID 29138487, 2017). "The asthma and obesity groups showed an increase in cytokine of IL-17A, IL-4, IL-6, TNF, IL-1β and IL-18 in the BALF compared with normal controls." (PMID 29160418, 2017). "We sought to investigate the role of neutrophils and the IL-17A pathway in mediating pediatric severe therapy-resistant asthma (STRA)." (PMID 27746241, 2017). "Our results suggested that elevated IL-17A and IL-9 expressions and decreased levels of adipsin and CCL11 were positively associated with adult asthma." (PMID 29138487, 2017). "In adults with severe asthma, high levels of IL-17A have been reported in sputum, BAL fluid, and peripheral blood, and this was associated with increased disease severity." (PMID 28725641, 2017). "The adjusted ORs (95%CI) of association between IL-17A, IL-9, adipsin and CCL11 expressions and adult asthma were 3.08 (1.91, 4.97), 1.93 (1.41, 2.64), 10.02 (6.99, 14.37) and 3.29 (2.36, 4.59), respectively (all Ptrend < 0.0001)." (PMID 29138487, 2017). "Collectively, these results suggest that IL-17A plays a central role in the pathophysiologies of certain asthma phenotypes." (PMID 28245275, 2017).
asthma (continued). "T-helper 17 (Th17) cells, a CD4+ helper T cell subset that produces interleukin-17a (IL-17A) have been discovered to play important roles in more severe asthma phenotypes." (PMID 28199353, 2017). "Compared to healthy controls, IL-17A expression was higher in cultured T-lymphocytes from patients with mild–moderate asthma and persistent allergic rhinitis and decreased after anti-inflammatory therapy with inhalative corticosteroids." (PMID 29201026, 2017). "Thus, IL-17A may be involved in corticosteroid responses to oxidant stress and IL-17A expression may underlie glucocorticoids insensitivity found in patients with severe asthma and COPD." (PMID 28194607, 2017). "The previous investigations also showed that IL-17A contributed to steroid insensitivity in patients with severe asthma." (PMID 28194607, 2017). "In this study, we observed that the plasma levels of IL-17A and IL-9 were significantly increased in asthma cases when compared with controls." (PMID 29138487, 2017). "Compared to moderate asthma, IL-4 expression was decreased and IL-17A expression was increased in severe asthma." (PMID 28808358, 2017). "Higher numbers of IL-17A–positive cells have been found in the bronchial submucosa from adults with severe asthma compared with controls." (PMID 27746241, 2017). "Accumulating evidence indicates that Th17 cell and Th17 cytokines such as IL-17A, IL-17F and IL-22 contribute to the development of asthma." (PMID 26974537, 2016). "Increasing evidence indicates that IL-17A is an important contributor to the development of asthma, especially to severe asthma characterized by airway intense neutrophil infiltration and less responsive to corticosteroids." (PMID 26974537, 2016). "Compared with IL-17A/IL-17 F, IL-17E plays an important role in the pathogenesis of asthma and atopic diseases through binding to the heterodimeric complex of IL-17RA/IL-17RB." (PMID 27716046, 2016). "Murine models of asthma suggest that IL-17A production by γδ T cells is anti-inflammatory and decreases the likelihood that a patient will experience airway hyperresponsiveness (AHR)." (PMID 27303404, 2016). "Lungs of humans with asthma have a characteristic expression pattern of inflammatory cytokines, notable amongst those IL-4, IL-6, IL-13, IL-17A and TNF-α50, 51, 52, indicative of Th2 cells and Th17 cells." (PMID 27087690, 2016). "TRAP-induced asthma is a distinct phenotype of asthma, which was recently shown by our group to be characterized by increased levels of serum IL-17A in children and increased CD4+IL13+IL17+ double-producing T effector memory cells in mice." (PMID 27777592, 2016). "In this work, the murine model of asthma was established with ovalbumin, and mice were intranasally vaccinated with rMS-Ag85a-IL-17a." (PMID 26974537, 2016). "As such, blocking or suppressing Th17 cell and their secretion of cytokines such as IL-17A appears to be a new direction in asthma therapy." (PMID 26974537, 2016). "Asthma is a chronic inflammatory disorder, previous studies have shown that IL-17A contributes to the development of asthma, and there is a positive correlation between the level of IL-17A and the severity of disease." (PMID 26974537, 2016). "More specifically, Tbet deficient T cells have been shown to drive airway IL-4 production and hyperreactivity in an asthma model and both IL-13 and IL-17A have been shown to be able to drive allergic airways disease in Tbet deficient mice." (PMID 27683080, 2016). "IL-17A can mediate steroid resistant inflammation and airway hyperresponsiveness whereas it can also negatively regulate established asthma." (PMID 25860963, 2015). "IL-17A, IL-17F and IL-22 are produced mainly by Th17 cells, and increased in the airways in steroid refractory severe asthma." (PMID 26131974, 2015). "Although increases in IL-17A expression were observed in the airway of severe asthma patients, the interaction between IL-17A and TLR activation in airway epithelium remains poorly understood." (PMID 26418032, 2015).